LRRFIP1 (LRR binding FLII interacting protein 1)
Description:
Transcriptional repressor which preferentially binds to the GC-rich consensus sequence (5'-AGCCCCCGGCG-3') and may regulate expression of TNF, EGFR and PDGFA. May control smooth muscle cells proliferation following artery injury through PDGFA repression. May also bind double-stranded RNA. Positively regulates Toll-like receptor (TLR) signaling in response to agonist probably by competing with the negative FLII regulator for MYD88-binding.
Synonyms: GCF2; TRIP; FLAP-1; FLIIAP1; GCF-2; HUFI-1; FLAP1
Tractability: Antibody: its Gene Ontology location is reachable by antibodies, with high confidence. PROTAC: UniProt records ubiquitination sites on it; ubiquitination databases record sites on it; its protein half-life has been measured.
Target class: Transcription factor
Gene: Protein-coding gene on chromosome 2 (237,627,554 to 237,813,682, forward strand). Ensembl gene ENSG00000124831.
Subcellular location: Nucleus; Cytoplasm
Subcellular location (Human Protein Atlas): Cytosol; Plasma membrane
Pathways (Reactome):
Disease: Signaling by FGFR1 in disease; Signaling by cytosolic FGFR1 fusion mutants
Immune System: LRR FLII-interacting protein 1 (LRRFIP1) activates type I IFN production
Gene Ontology:
Molecular function: cadherin binding; DNA binding; DNA-binding transcription repressor activity, RNA polymerase II-specific; protein binding; protein homodimerization activity; RNA polymerase II cis-regulatory region sequence-specific DNA binding; DNA-binding transcription factor activity, RNA polymerase II-specific; double-stranded RNA binding
Biological process: negative regulation of transcription by RNA polymerase II; regulation of DNA-templated transcription
Cellular component: cytosol; nucleus; cytoplasm; cytoskeleton
Genetic constraint (gnomAD): Loss-of-function variants: 36 observed, 58.44 expected, observed/expected ratio (o/e) 0.62, 90% interval 0.47 to 0.81. The upper end of that interval is the gene's LOEUF score, 0.81, which puts it in group 3 of 6, group 1 being the genes least tolerant of losing a copy. Missense variants: 652 observed, 642.42 expected, observed/expected ratio (o/e) 1.01, 90% interval 0.95 to 1.08. Synonymous variants: 255 observed, 239.48 expected, observed/expected ratio (o/e) 1.06, 90% interval 0.96 to 1.18.
Homologues: Orthologues: guinea pig LRRFIP1 (83% identical), rabbit LRRFIP1 (74% identical), rat Lrrfip1 (72% identical), dog LRRFIP1 (60% identical), tropical clawed frog lrrfip1 (58% identical), chimpanzee LRRFIP1 (49% identical), macaque LRRFIP1 (49% identical), zebrafish lrrfip1a (41% identical), mouse Lrrfip1 (37% identical), Drosophila melanogaster CG8578 (27% identical), Caenorhabditis elegans flap-1 (19% identical). Paralogues in human: LRRFIP2 (53% identical).
Diseases named in the same sentence as LRRFIP1 in open-access papers:
LRRFIP1 is named in the same sentence as 54 diseases in open-access papers, as found by Europe PMC text mining. Sharing a sentence is not in itself a finding about the gene and the disease. The quoted sentences say what the papers report.
glioblastoma (10 papers, 2010 to 2024). The most malignant astrocytic tumor (WHO grade IV). "Because LRRFIP1 has been linked to immune responses in infectious diseases and glioblastoma, we proposed the hypothesis that it may play a role in pancreatic cancer tumor immunity." (PMID 38634978, 2024). "High expression of LRRFIP1 was found to be associated with a better response to teniposide in glioblastoma, and could be a candidate gene for tumor-targeted therapy." (PMID 36555319, 2022). "Survival analysis revealed eight RBPs (PTRF, FNDC3B, SLC25A43, ZC3H12A, LRRFIP1, HSP90B1, HSPA5, and BNC2) are significantly associated with the survival of glioblastoma patients." (PMID 32272554, 2020). "Furthermore, LRRFIP1 has recently been identified as the key response prediction gene of PD-1 inhibitors in glioblastoma." (PMID 38634978, 2024). "Moreover, miR-21 in glioblastoma cells can target LRRFIP1 and thereby facilitate NFκB pathway activation, while silencing miR-21 can strengthen the anti-tumour effects of sunitinib (a tyrosine kinase inhibitor) in U87 human glioblastoma cells." (PMID 35421166, 2022). "Enforced expression of miR-21 could also induce chemoresistance in glioblastoma multiforme cells by targeting LRRFIP1." (PMID 24788655, 2014). "MiR-21 targets LRRFIP1 (LRR Binding FLII Interacting Protein 1) and promotes teniposide resistance (VM-26) in glioblastoma." (PMID 35330864, 2022). "In glioblastoma multiforme (GBM), a human malignant brain tumor, the resistance to a topoisomerase II inhibitor teniposide (VM-26) was mediated by the over-expression of a microRNA, miR-21, which binds in the 3′-untranslated region (UTR) of LRRFIP1/GCF2 and down-regulates its expression." (PMID 30709060, 2019).
colorectal cancer (3 papers, 2019 to 2023). A primary or metastatic malignant neoplasm that affects the colon or rectum. "LARG binds to LRRFIP1/GCF2 and mediates the integrin signaling pathway, causing RhoA activation, leading to the stimulation of cytoskeletal remodeling, increased migration, and invasion of metastatic colorectal cancer cells." (PMID 30709060, 2019). "RhoA plays a role in regulating downstream in the integrin signaling pathway, and knockdown of LRRFIP1/GCF2 reduced activation of RhoA in the colorectal cancer cells plated on fibronectin-coated dishes." (PMID 30709060, 2019). "LRRFIP1 promoted colorectal cancer metastasis and liver invasion through RhoA activation." (PMID 35338570, 2022). "Inhibitions of LRRFIP1/GCF2 by the transfection of short inhibitory RNA (siRNA) into a cervical carcinoma and colorectal cancer cell lines have been shown to reduce RhoA activation, migration, and cytoskeletal remodeling of the transfected cell lines." (PMID 30709060, 2019). "LRRFIP1/GCF2 promoted metastasis and liver invasion of human colorectal carcinoma cell lines transplanted in mice through RhoA activation." (PMID 30709060, 2019).
COVID-19 (3 papers, 2022 to 2025). A disease caused by infection with severe acute respiratory syndrome coronavirus 2. "Moreover, we observed a significant ES event of LRRFIP1 in the ICU cohort (p = 0.009), suggesting that AS of LRRFIP1 is a prevalent signature in severe COVID-19 patients." (PMID 35421082, 2022). "Notably, CD74 and LRRFIP1 had increased skipping of an exon in COVID-19 patients that disrupts a functional domain, which correlated with reduced antiviral immunity." (PMID 35421082, 2022). "In addition, we deployed validation experiments for local splicing changes of 6 genes (CD74, LRRFIP1, SH3GLB1, MACF1, RPS24 and PDLIM5) between 9 COVID-19 cases and 10 controls by semiquantitative reverse transcription (RT)-PCR." (PMID 35421082, 2022). "The cytosolic nucleic acids sensor LRRFIP1 mediates the production of type I interferon, which plays an important role in exacerbating TNF- and IL-1-driven inflammation in the progression to severe COVID-19." (PMID 35421082, 2022).
hepatocellular carcinoma (3 papers, 2019 to 2024). A malignant tumor that arises from hepatocytes. "In terms of prognosis, upregulation of LRRFIP1 has been associated with poor overall survival in gliomas and hepatocellular carcinoma." (PMID 38634978, 2024). "LRRFIP1 was highly expressed in most primary human hepatocellular carcinoma (HCC) tissues and HCC cell lines." (PMID 35338570, 2022).
lung carcinoma (3 papers, 2016 to 2019). "Co-expression analysis revealed that ACSL1 was coexpressed with MYBPH, PTPRE, PFKFB3, SOCS3 in colon cancer and with LRRFIP1, TSC22D1 in lung cancer." (PMID 27171439, 2016). "As for lung cancer, ACSL1 was coexpressed with leucine rich repeat (in FLII) interacting protein 1 (LRRFIP1) and TSC22 domain family member 1 (TSC22D1)." (PMID 27171439, 2016). "Studies have suggested that increased LRRFIP-1 levels may affect cell behavior, and high levels of LRRFIP-1 have been observed in liver and lung cancers, with LRRFIP-1 being shown to promote cancer metastasis and cancer cell invasion." (PMID 29996558, 2018). "Knockdown of LRRFIP1/GCF2 reversed EMT, with the increased expression of E-cadherin, an epithelial marker, and the decreased expression of vimentin, a mesenchymal marker, and the migration and invasion capacities of pancreatic and lung cancers being significantly inhibited." (PMID 30709060, 2019).
myocardial infarction (3 papers, 2014 to 2021). Gross necrosis of the myocardium, as a result of interruption of the blood supply to the area, as in coronary thrombosis. "Also, KODA-PC induced dephosphorylation of LRRFIP1 at Ser115, a protein with variations in human platelets that affects platelet reactivity and is associated with myocardial infarction." (PMID 24400094, 2014). "Furthermore, an association study of several of these genes showed a putative association with myocardial infarction for COMMD7 (COMM domain-containing protein 7) and a highly significant association for LRRFIP1 (leucine-rich repeat (in FLII) interacting protein 1)." (PMID 33725119, 2021).
pancreatic cancer (3 papers, 2019 to 2023). "LRRFIP1 increased the EMT in pancreatic cancer through the Wnt/β‐catenin pathway." (PMID 35338570, 2022). "LRRFIP1/GCF2 was shown to promote EMT in pancreatic cancer through the Wnt/β-catenin pathway." (PMID 30709060, 2019). "We also found that pancreatic cancer patients with elevated expression of MAPK1, LRRFIP1, SP110, and NFE2 had a decreased rate of survival relative to patients with lower expression of these genes." (PMID 37627195, 2023).
Stroke (3 papers, 2019 to 2025). Sudden impairment of blood flow to a part of the brain due to occlusion or rupture of an artery to the brain. "Dysregulations of LRRFIP1/GCF2 have been implicated in the causes of several experimental and clinico-pathological states and the responses to them, such as autoimmune diseases, excitotoxicity after stroke, thrombosis formation, inflammation and obesity, the wound healing process, and in cancers." (PMID 30709060, 2019). "The kinase’s activity is modulated by various factors, including its interaction with other proteins such as Leucine-Rich Repeat Flightless-1 Interacting Protein 1(LRRFIP1), which has been identified as a novel interactor in stroke-like conditions." (PMID 40918124, 2025). "Furthermore, it has been reported that a prevalent polymorphism in the promoter of the glutamate transporter EAAT2 gene creates a new consensus binding site for LRRFIP1, which impairs glutamate uptake in astrocytes and increases the frequency of early neurological worsening in stroke." (PMID 33265962, 2020).
atherosclerosis (2 papers, 2019 to 2023). A disease characterized by the build-up of fatty material and calcium deposition in the arterial wall resulting in partial or complete occlusion of the arterial lumen. "We found that UCA1 was increased in atherosclerosis and may upregulate Lrrfip1 by sponging miR-132 to promote the proliferation of VSMCs." (PMID 37533737, 2023). "In conclusion, UCA1 is upregulated in atherosclerosis and it may sponge miR-132 to upregulate Lrrfip1, thereby promoting the proliferation of VSMCs." (PMID 37533737, 2023). "Therefore, UCA1 is downregulated in atherosclerosis and may regulate miR-132/Lrrfip1 axis to promote VSMC proliferation." (PMID 37533737, 2023).
breast carcinoma (2 papers, 2007 to 2012). "In current study we analyzed six previously identified medullary breast carcinoma autoantigens including LGALS3BP, RAD50, FAM50A, RBPJ, PABPC4, LRRFIP1 with cancer restricted serological profile in different histological types of breast cancer." (PMID 23181716, 2012). "Similarly, the presence of ABCB10 and NUP133, and candidate tumor suppressors LRRFIP1 and RNU3IP2 in the RB1-related cluster, further support their functional association in breast cancer." (PMID 17280605, 2007). "Thus, during this study we described for the first time expression patterns of 6 potential MBC-associated antigens, including LGALS3BP, RAD50, FAM50A, RBPJ, PABPC4, LRRFIP1 in different histological types of breast carcinomas and non-cancerous breast tissues by immunohistochemical analysis." (PMID 23181716, 2012).
cervical carcinoma (2 papers, 2019 to 2022). A carcinoma arising from either the exocervical squamous epithelium or the endocervical glandular epithelium. "Nomograms have been proved LRRFIP1 as a more accurate prognostic prediction in cholangiocarcinoma and cervical cancer." (PMID 35338570, 2022).
glioma (2 papers, 2022 to 2024). A benign or malignant brain and spinal cord tumor that arises from glial cells (astrocytes, oligodendrocytes, ependymal cells). "Based on TCGA, CGGA, and REMBRANDT databases, we screen a significant prognostic methylation gene of LRRFIP1 for an independent risk factor in gliomas." (PMID 35338570, 2022). "In conclusion, LRRFIP1 could provide diagnostic or prognostic information for gliomas, possibly also act as a new therapeutic target in gliomas." (PMID 35338570, 2022). "LRRFIP1 expression was an independent risk factor for OS (overall survival) in gliomas." (PMID 35338570, 2022). "The elevated LRRFIP1 expression was clinically correlated with unfavorable outcomes of glioma patients in all grades, LGG and GBM based on TCGA RNAseq database." (PMID 35338570, 2022). "The expression of LRRFIP1 was different among those subtypes of glioma in CGGA and TCGA RNAseq databases." (PMID 35338570, 2022). "We also detected the protein level of LRRFIP1 in clinical glioma specimens, and positive expression of LRRFIP1 was located in cytoplasm and nucleus of tumor cells." (PMID 35338570, 2022). "The results demonstrated that high LRRFIP1 expression was negatively correlated with glioma patients’ survival probability in all grades, LGG and GBM based on CGGA RNAseq database (p < 0.001)." (PMID 35338570, 2022). "GO (Gene Ontology) and KEGG (Kyoto Encyclopedia of Genes and Genomes) pathway were performed to explore functions and related mechanisms of LRRFIP1 in gliomas." (PMID 35338570, 2022). "We explored univariate and multivariate cox proportional hazard models to anticipate LRRFIP1 prognosis for glioma patients in CGGA RNAseq database." (PMID 35338570, 2022). "In our study, we focus the potential prognostic value of LRRFIP1, giving new insights into the methylation role of LRRFIP1 in glioma." (PMID 35338570, 2022). "We show how the value of LRRFIP1 can lead to better predictive models, and a deeper understanding of the function of methylation in gliomas." (PMID 35338570, 2022). "LRRFIP1 expression levels enriched in high‐grade gliomas comply with malignancy character." (PMID 35338570, 2022). "COX analysis verified that LRRFIP1 acts as an independent prognosis factor in gliomas." (PMID 35338570, 2022). "Nomogram models were also performed to identify LRRFIP1 prognostic value in gliomas." (PMID 35338570, 2022). "LRRFIP1 expression increased with tumor grade, especially concentrated in high‐grade gliomas." (PMID 35338570, 2022). "The GO and KEGG function analysis revealed that LRRFIP1 may play important roles in glioma progression." (PMID 35338570, 2022). "LRRFIP1 is an epigenetically regulated gene and a potential prognostic biomarker for glioma." (PMID 35338570, 2022). "Collectively, these results indicated that LRRFIP1 was correlated with clinical features of glioma." (PMID 35338570, 2022). "Patients with low methylation level of LRRFIP1 correlated with worse prognosis in all gliomas." (PMID 35338570, 2022). "The detailed understanding of LRRFIP1 by epigenetically regulation may uncover a new direction for anti‐glioma therapy." (PMID 35338570, 2022). "In summary, our findings disclosed that LRRFIP1 may serve as an important factor in drug selection and prognostic judgment of glioma patients." (PMID 35338570, 2022). "LRRFIP1 significantly enriched in high‐grade gliomas in TCGA, CGGA, and REMBRANDT databases, our results indicated that LRRFIP1 may act as the malignancy characters in glioma and closely relate to clinical outcomes." (PMID 35338570, 2022). "High LRRFIP1 expression indicated worse prognosis in all gliomas, LGG and GBM." (PMID 35338570, 2022). "However, the methylation and expression status of LRRFIP1, especially the function in glioma biology, are still unknown." (PMID 35338570, 2022). "In summary, LRRFIP1 may play a vital role in glioma progression." (PMID 35338570, 2022).
glioma (continued). "In order to understand the distribution of LRRFIP1 mRNA expression in GBM, we explored the LRRFIP1 mRNA expression in glioma's clinical features." (PMID 35338570, 2022). "Therefore, significant differences existed in the negative correlation between LRRFIP1 expression and DNA methylation among glioma cell lines." (PMID 35338570, 2022).
ischemia (2 papers, 2019 to 2020). A hypoperfusion of the BLOOD through an organ or tissue caused by a PATHOLOGIC CONSTRICTION or obstruction of its BLOOD VESSELS, or an absence of BLOOD CIRCULATION. "In fact, several cross-IP assays (IP with antibodies against DAPK1 or LRRFIP1) revealed an association and coexistence of the 2 proteins after ischemia in adult rat brain or after OGD or NMDA treatment in primary culture neurons." (PMID 33265962, 2020). "Second, and most important, LRRFIP1 has been previously observed upregulated in ischemia models, either in vivo or in cultured astrocytes." (PMID 33265962, 2020). "Our results suggest that the increase in LRRFIP1 expression precedes neuronal death as a common characteristic of ROS-generating challenges, involving either fast (ischemia/ischemia-like and excitotoxicity) or slow (ferroptosis) mechanisms of neuronal death." (PMID 33265962, 2020). "Among them, we selected LRRFIP1 as a good candidate since it had been previously reported overexpressed in astrocytes exposed to ischemia." (PMID 33265962, 2020). "The induced expression of LRRFIP1/GCF2 must be playing a positive role in the recovery of brain from ischemia by mediating these molecules." (PMID 30709060, 2019). "We have identified for the first time LRRFIP1 as a DAPK1 partner, which we found up-regulated by OGD in the neuronal DAPK1 interactome, this being in line with the previously reported involvement of LRFFIP1 in ischemia." (PMID 33265962, 2020).
Obesity (2 papers, 2019 to 2024). Accumulation of substantial excess body fat. "Another important finding of the present study is that Lrrfip1, known to be associated with obesity, was upregulated with FGR and requires further investigation." (PMID 39627016, 2024). "Another important finding of the present study is that Lrrfip1, associated with obesity, was upregulated with FGR and requires further investigation." (PMID 39627016, 2024). "Several single nucleotide polymorphism (SNP) variants of LRRFIP1/GCF2 have been shown to be associated with phenotypes for obesity and inflammation." (PMID 30709060, 2019). "Another important gene that could provide immunity to MFGR from the future development of obesity is LRRFIP1." (PMID 39627016, 2024).
Sepsis (2 papers, 2023 to 2024). Sepsis is defined as life-threatening organ dysfunction caused by a dysregulated host response to infection. "MiR-215-5p expression is protective in inflammation injury that occurs in sepsis caused by H9c2 by targeting ILF3 and LRRFIP1." (PMID 37749550, 2023). "Interestingly, miR-215-5p protects against sepsis-induced myocardial inflammation in LPS-treated H9c2 cells through targeting ILF3 and LRRFIP1." (PMID 38395749, 2024).
viral infection (2 papers, 2020 to 2023). "LRRFIP1 rapidly colocalises with viruses and interacts transiently with viral sensing Toll-like receptor 3 (TLR3) following viral infection." (PMID 33330501, 2020). "While viral infection with Hepatitis C (HCV) in the cells does not alter expression of LRRFIP1 itself, the induction of IFN by LRRFIP1 is also exacerbated by HCV infection, and the upregulation of IFN acts to inhibit the replication of the virus." (PMID 33330501, 2020).